BASP1 (brain abundant membrane attached signal protein 1)
Diseases named in the same sentence as BASP1 in open-access papers (continued):
Sharing a sentence is not in itself a finding about the gene and the disease.
leukemia (6 papers, 2009 to 2024). A malignant (clonal) hematologic disorder, involving hematopoietic stem cells and characterized by the presence of primitive or atypical myeloid or lymphoid cells in the bone marrow and the blood. "Having identified the myristoylated N‐terminal BASP1 peptide as a reagent to selectively interfere with the viability of v‐myc‐transformed cells, we explored if Myr‐NT would also inhibit the growth of leukemia cells containing high levels of endogenous MYC." (PMID 31944520, 2020). "The BASP1 gene is downregulated in many human tumor cell lines particularly in those derived from leukemias, which display elevated levels of WT1 and of the major cancer driver MYC." (PMID 31058089, 2019). "Critically, PSMB8 was responsible for the self-renewal capacity of leukemia stem cells and the initiation of MLL-rearranged leukemia by regulating the DNA binding with brain abundant membrane attached signal protein 1 (BASP1), positioning it as a promising target for anti-leukemia therapy." (PMID 39335660, 2024). "Because the orthologous human BASP1 promoter has a similar structure, and BASP1 is downregulated in a variety of human leukemia cells containing elevated MYC levels, human BASP1 transcription may be repressed by a similar mechanism." (PMID 31058089, 2019). "Increased abundance of BASP1 attenuated growth of KMT2A-r AML cells in vitro and reduced leukemia formation in humanized recipient mice." (PMID 38049829, 2023). "In the original study, two of these genes were found as differentiating among two leukemia subtypes (BASP1 and CYB5A) and the other three were never mentioned." (PMID 19146700, 2009).
gastric cancer (4 papers, 2020 to 2023). A primary or metastatic malignant neoplasm involving the stomach. "Our research is designed to explore the function of brain acid soluble protein 1 (BASP1) in the progression of gastric cancer (GC) and its underlying molecular mechanisms." (PMID 33426068, 2020). "BASP1 is highly expressed in gastric cancer and can be used as an independent indicator to predict poor overall survival in patients with gastric cancer." (PMID 37243901, 2023). "BASP1 is a membrane‐bound protein that plays a promotional or inhibitory role in a variety of tumors; however, its role in gastric cancer (GC) and in the immune microenvironment has not been reported." (PMID 37243901, 2023). "Finally, we found that the imbalance of 11 immune regulatory factors could predict the overall survival time of gastric cancer, including EZH2, NRP1, CD59, OsBPL1aBCL11B, BASP1, HNMT, CXCR4, ASGR2, ANXA5, CDH2." (PMID 34322132, 2021).
lung adenocarcinoma (4 papers, 2019 to 2024). A carcinoma that arises from the lung and is characterized by the presence of malignant glandular epithelial cells. "Taken together, these data indicate that BASP1 is associated with poor outcomes in patients with lung adenocarcinoma and that its expression is enriched after metastasis to the brain." (PMID 33042262, 2020). "It has been reported that BASP1 is an adverse prognostic factor, because its overexpression in lung adenocarcinoma tissues promotes the proliferation and migration of cancer cells, which is closely related to poor prognosis." (PMID 38443340, 2024). "We further analyzed BASP1 expression in a human lung adenocarcinoma tissue microarray by IHC and showed that lung tumors exhibited higher BASP1 expression than adjacent normal lung tissues (P < 0.001)." (PMID 33042262, 2020). "Analysis of a dataset of lung adenocarcinoma specimens from the TCGA database indicated that samples with high BASP1 expression exhibited significantly elevated EGFR signaling (left)." (PMID 33042262, 2020). "Moreover, analysis of the lung adenocarcinoma dataset from The Cancer Genome Atlas (TCGA) also indicated significantly higher levels of BASP1 in lung cancers than in normal lung tissues." (PMID 33042262, 2020). "The clinical relevance of BASP1 in lung adenocarcinoma was first assessed." (PMID 33042262, 2020).
lung carcinoma (4 papers, 2020 to 2021). "All these data suggest that BASP1-abundant lung cancer cells facilitate EGFR signaling amplification than BASP1-deficient cells." (PMID 33042262, 2020). "We investigated the function of BASP1 in metastatic lung cancer cells, focusing on the interaction between EGFR and BASP1, and searched for potential drugs to target the BASP1-EGFR axis to overcome TKI resistance in lung cancer." (PMID 33042262, 2020). "Taken together, these results demonstrate that the expression of BASP1 can foster lung cancer metastasis." (PMID 33042262, 2020). "Next, we evaluated the effects of BASP1 knockdown on EGFR inhibitors in different lung cancer cell lines that included EGFR-mutant and EGFR-WT cells." (PMID 33042262, 2020). "The results indicated that depletion of BASP1 expression reduced proliferation in several lung cancer cell lines, including Bm7, A549, H2981, and PC9 cells." (PMID 33042262, 2020). "We first validated the specificity of the BASP1 antibody in BASP1-knockdown A549 and BASP1-overexpressing CL1-0 lung cancer cells with transient transfection of BASP1-GFP." (PMID 33042262, 2020). "In this study, we revealed a novel mechanism of BASP1 in promoting lung cancer malignancy: BASP1 enriches EGFR in lipid rafts and enhances EGFR signaling by reducing CBL-dependent EGFR ubiquitination." (PMID 33042262, 2020). "Together, these results support the notion that BASP1 promotes the tumorigenesis of lung cancer cells in vitro and in vivo." (PMID 33042262, 2020). "Lastly, arsenic trioxide and EGFR TKIs reduce BASP1 expression and induce a synergistic inhibitory effect in lung cancer cells with acquired resistance to EGFR inhibitors." (PMID 33042262, 2020). "Increasing evidence has confirmed that BASP1, a potential tumor suppressor, plays an important role in a variety of cancers, such as thyroid cancer, liver cancer, and lung cancer." (PMID 33426068, 2020). "In contrast, ectopic expression of BASP1 in lung cancer cells increased the levels of endogenous EGFR, phospho-EGFR, phospho-ERK, and phospho-AKT." (PMID 33042262, 2020). "More and more pieces of evidence confirm that BASP1 plays as a potential suppressor of tumor and functions importantly in various carcinomas, including thyroid carcinoma, stomach carcinoma and lung carcinoma." (PMID 34322132, 2021). "Targeting the newly identified BASP1-EGFR interaction could open new venues for lung cancer treatment." (PMID 33042262, 2020). "Given that aberrant EGFR signaling is a significant driver of lung cancer and that approximately 50% of Asian patients with NSCLC harbor EGFR mutations, we further investigated whether BASP1 regulates EGFR signaling." (PMID 33042262, 2020). "Additionally, transient transfection of mouse shRNA-resistant GFP-tagged BASP1 into mouse BASP1-knockdown TC1 lung cancer cells restored cell proliferation." (PMID 33042262, 2020). "Similarly, our findings showed that As2O3 reduced BASP1 expression and induced synergistic effects to kill lung cancer cells when combined with EGFR TKIs." (PMID 33042262, 2020). "Moreover, the synergistic therapeutic effects of EGFR tyrosine kinase inhibitor and arsenic trioxide led to a reduction in the level of BASP1 protein observed in lung cancer cells with acquired resistance to EGFR inhibitors." (PMID 33042262, 2020). "However, our findings demonstrated that most BASP1 exists in the cytosol and lipid rafts to promote cell survival of malignant lung cancer cells." (PMID 33042262, 2020). "Furthermore, BASP1 decreases the drug sensitivity of lung cancer cells treated with EGFR tyrosine kinase inhibitors (TKIs) (erlotinib and afatinib)." (PMID 33042262, 2020). "In contrast, overexpressing BASP1 (OE BASP1) increased the proliferative abilities of A549 cells and HCC827 lung cancer cells compared to those in control cells (dose-dependent increase)." (PMID 33042262, 2020).
lung carcinoma (continued). "By focusing on the critical RTK in lung cancer, EGFR, we demonstrated that positive feedback between BASP1 and EGFR amplified the signaling in the lipid raft." (PMID 33042262, 2020). "Our studies showed that BASP1 knockdown decreased calcium influx in lung cancer cells treated with EGF, suggesting that BASP1 enhanced EGFR signaling and calcium influx to increase cell migration." (PMID 33042262, 2020). "Therefore, simultaneously blocking BASP1 and EGFR signaling with EGFR tyrosine kinase inhibitors were expected to suppress the metastasis of lung cancer cells by suppressing calcium influx." (PMID 33042262, 2020). "Indeed, our study revealed that targeting BASP1 interrupted the RTK co-activation and further lead to the lethal effects of lung cancer cells treated with RTK inhibitors." (PMID 33042262, 2020). "To investigate whether BASP1 activates membrane RTK signaling, we used a human phospho-RTK array to compare the relative signal intensities of phospho-RTKs between control and IPTG-induced BASP1-knockdown cells in two lung cancer cell lines." (PMID 33042262, 2020).
diabetic nephropathy (3 papers, 2015 to 2025). "Basp1 (brain abundant, membrane attached signal protein 1), encoding a membrane attached signaling protein, within module IV was originally identified as a transcriptional corepressor of Wt1 (Wilms’ tumor) that promoted apoptosis in diabetic nephropathy." (PMID 28931758, 2017). "Interestingly, not all tubules were BASP1-positive: there were BASP1-positive and BASP1-negative tubules within the same diabetic nephropathy biopsy." (PMID 25675304, 2015).
head and neck squamous cell carcinoma (3 papers, 2020 to 2023). A squamous cell carcinoma that arises from any of the following anatomic sites: lip and oral cavity, nasal cavity, paranasal sinuses, pharynx, larynx, and salivary glands. "High expression of BASP1 is associated with poor prognosis of human LUAD and head and neck squamous cell carcinoma and promotes tumor progression." (PMID 36147484, 2022). "However, the role of BASP1 in head and neck squamous cell carcinoma (HNSCC) is largely unknown." (PMID 33247706, 2020).
Obesity (3 papers, 2017 to 2025). Accumulation of substantial excess body fat. "In another study, a GWAS conducted on 1996 adult CCS (median age at diagnosis, 7.2 years; median age at follow-up, 32.4 years) identified potential obesity-associated loci on chromosomes 13 (FAM155A), 2 (SOX11), 4 (GLRA3), and 5 (CDH18, BASP1), particularly among CRT-exposed survivors." (PMID 41228239, 2025).
thyroid cancer (3 papers, 2017 to 2021). "For example, the expression of BASP1 is reported to be downregulated in thyroid cancer tissues." (PMID 33426068, 2020).
dementia (2 papers, 2016 to 2017). Loss of intellectual abilities interfering with an individual's social and occupational functions. "These dementia-specific HCit-containing proteins include brain acid soluble protein 1 (BASP1), spectrin alpha chain 1 (SPTAN1), and glial fibrillary acidic protein (GFAP)." (PMID 28865468, 2017).
glioblastoma (2 papers, 2015 to 2018). The most malignant astrocytic tumor (WHO grade IV). "Conversely, RNAs overexpressed in LTCs vs LTPs showed an enrichment in markers of the neural subtype of glioblastoma, such as BASP1, CDC42, and SH3GL2." (PMID 26188123, 2015).
metastatic tumor (2 papers, 2020 to 2025). "Analysis of primary and brain-metastatic tumor specimens from patients with NSCLC indicated that BASP1-positive samples also had strong EGFR staining." (PMID 33042262, 2020). "Notably, increased expression of BASP1 has been detected in the 61.5% metastatic tumor." (PMID 40076916, 2025).
pancreatic cancer (2 papers, 2020). "Recent studies showed that WT1 is activated in pancreatic cancer and that patients with elevated BASP1 levels have a significantly better prognosis than individuals whose cancer cells contain no BASP1 but high WT1 levels." (PMID 31944520, 2020). "In pancreatic cancer, expression of BASP1 prolongs survival whereas tumors with no BASP1 but high WT1 expression indicate a poor prognosis." (PMID 31944520, 2020).
Parkinson disease (2 papers, 2020 to 2022). A progressive degenerative disorder of the central nervous system characterized by loss of dopamine producing neurons in the substantia nigra and the presence of Lewy bodies in the substantia nigra and locus coeruleus. "In the following sections, GAP-43 and BASP1 will be discussed in the context of Alzheimer’s and Parkinson’s Disease, two neurodegenerative diseases in which they have been studied the most." (PMID 33015061, 2020).
prostate carcinoma (2 papers, 2013 to 2020). A carcinoma that arises from epithelial cells of the prostate gland. "BASP1 is a Wilms' tumor suppressor protein (WT1)-associated factor that can regulate WT1 transcriptional activity and it may be a potential target for prostate cancer therapy." (PMID 23717685, 2013).
Wilms tumor (2 papers, 2017 to 2024). An embryonal neoplasm characterized by the presence of epithelial, mesenchymal, and blastema components. "Through interactions with WT1, a key transcription factor implicated in Wilms’ tumour, BASP1 and WT1 promote tumour-suppressing gene expression, induce cell differentiation, and upregulate genes for neurite outgrowth." (PMID 38398114, 2024).
atherosclerosis (1 paper, 2023). A disease characterized by the build-up of fatty material and calcium deposition in the arterial wall resulting in partial or complete occlusion of the arterial lumen. "Additional GWAS hits in the shared cross-species CAD/atherosclerosis subnetworks were peripheral nodes (e.g. CETP, PLCG2, BASP1, MSR1, ST5, ASAP2)." (PMID 38060277, 2023).
brain cancer (1 paper, 2023). A primary or metastatic malignant neoplasm affecting the brain. "BASP-1 is a protein encoded by the BASP1 gene and has been found to be part of the Wnt/Beta-catenin signaling pathway, which plays a crucial role in the development of various cancers, including gastric and brain cancers." (PMID 37894372, 2023).
cervical tumor (1 paper, 2017). "Overexpression of BASP1 promoted cervical tumor growth in the nude mice, and downregulation of BASP1 inhibited it." (PMID 29089860, 2017).
chronic lymphocytic leukemia (1 paper, 2020). "In acute and chronic lymphocytic leukemia, BASP1 expression is downregulated 42, 43, suggesting a tumor suppressive role of BASP1." (PMID 33042262, 2020).
colon cancer (1 paper, 2026). "Starting from human colon cancer cells showing aberrant WNT/β-catenin/TCF signaling, hyperactivated MYC, and silenced BASP1, we generated stable cell lines overexpressing BASP1, either ectopically, or by reactivating the dormant BASP1 promoter using a lentiviral CRISPR-based system." (PMID 41785318, 2026).
glioma (1 paper, 2013). A benign or malignant brain and spinal cord tumor that arises from glial cells (astrocytes, oligodendrocytes, ependymal cells). "And the target genes for SOX2 binding regions in glioma cells were identified, such as ARRDC4, PDE4D, BASP1 and so on." (PMID 24565222, 2013).
large cell neuroendocrine carcinoma (1 paper, 2025). A usually aggressive carcinoma composed of large malignant cells which display neuroendocrine characteristics. "In particular, a recent review highlighted the expression of ENOB with other three proteins, namely BASP-1 (brain acid soluble protein 1), AL1A1 (aldehyde dehydrogenase 1A1), and SEGN (secretagogin), in both small-cell lung cancer (SCLC) and large cell neuroendocrine carcinoma (LCNE)." (PMID 40869249, 2025).
membranous nephropathy (1 paper, 2015). "Moreover, data collected in the Nephromine database showed that in 21 patients with membranous nephropathy (eGFR 85±40 ml/min/1.73 m2, age 54±18 years, 12 males/9 females), tubulointerstitial BASP1 mRNA expression was found to be 1.204-fold (P=0.012) that of healthy living kidney donors." (PMID 25675304, 2015).
nephrotic syndrome (1 paper, 2015). A collection of symptoms that include severe edema, proteinuria, and hypoalbuminemia; it is indicative of renal dysfunction. "In rat nephrotic syndrome, BASP1 protein expression increased to a higher degree that mRNA expression." (PMID 25675304, 2015). "BASP1 expression was studied in experimental puromycin aminonucleoside-induced nephrotic syndrome in rats and in human nephrotic syndrome." (PMID 25675304, 2015).
oral squamous cell carcinoma (1 paper, 2026). "Overall, our study demonstrates that BASP1 acts as a key regulator of EMT in cisplatin-resistant oral squamous cell carcinoma and represents a promising therapeutic target to overcome drug resistance in advanced stages of the disease." (PMID 41506484, 2026).
primary immunodeficiency (1 paper, 2023). "In addition, GO, KEGG, and GESA enrichment analyses suggested that BASP1 may be involved in ‘regulation of T‐cell activation’, ‘primary immunodeficiency’, and other processes that are highly related to the immune response." (PMID 37243901, 2023).
Stroke (1 paper, 2020). Sudden impairment of blood flow to a part of the brain due to occlusion or rupture of an artery to the brain. "The upregulation of GAP-43 and BASP1 also correlated with axonal sprouting after stroke in the barrel cortex." (PMID 33015061, 2020). "Given that BASP1 is similarly upregulated after stroke, its increase may also be mediated by NGF and BDNF." (PMID 33015061, 2020).